MCL1 (MCL1 apoptosis regulator, BCL2 family member)
Diseases named in the same sentence as MCL1 in open-access papers (continued):
Sharing a sentence is not in itself a finding about the gene and the disease.
cancer (continued). "Several natural compounds have demonstrated promising effects in modulating MCL-1 to induce cancer cell death." (PMID 41049425, 2025). "This pathway enhances the expression of anti-apoptotic proteins, such as BCL-2 and MCL-1, and inhibits pro-apoptotic signals, providing a survival advantage to cancer cells in the face of chemotherapeutic stress." (PMID 40149289, 2025). "Conversely, ABT-263/navitoclax-resistant TIS cancer cells show a compensatory MCL-1 upregulation, serving as a resistance mechanism against ABT-263/navitoclax-induced apoptosis." (PMID 41280927, 2025). "Inhibition of MEK/ERK signaling leads to BIM accumulation and increases apoptotic priming in oncogene-driven cancers treated with various targeted therapies, driving cells into an MCL-1 and/or BCL-XL dependent state." (PMID 40316540, 2025). "In response to venetoclax-induced pressure, cancer cells often shift their apoptotic dependencies by increasing expression of MCL1, BCLXL, or BCL2A1." (PMID 41155156, 2025). "As cell models, we used ex vivo samples from patients and also selected the in vitro CLL cell line Mec-1, generating two sub-lines overexpressing Bcl-XL and Mcl-1, a common feature in this cancer." (PMID 40940754, 2025). "Proteasome inhibition induces apoptosis in cancer, and we have recently described the role of the anti-apoptotic factors MCL-1 and BCL-xL in treatment resistance in TH and TC." (PMID 41339338, 2025). "This review specifically focuses on resistance to BCL2 and MCL1 inhibitors, given their clinical relevance in cancer therapy." (PMID 41155156, 2025). "One prominent example is the granzyme B-NOXA fusion protein, which delivers the BH3-only protein via the perforin-granzyme axis and selectively antagonizes the anti-apoptotic MCL-1 protein in target cancer cells." (PMID 41280927, 2025). "The apoptosis assay displayed the role of compound 24 in reducing the levels of BCL-2 and MCL-1, which led to apoptosis of the cancer cells." (PMID 40283934, 2025). "The PI3K/AKT signaling pathway is a common molecular route that links the ABCG2, CYP3A4, and MCL1 genes, particularly in the contexts of cancer and drug resistance." (PMID 39931465, 2025). "This is consistent with previous studies in other cancer models, where MCL1 was shown to limit ferroptosis by directly binding and inactivating BECN1." (PMID 41008795, 2025). "PI3K inhibition can effect diverse cellular changes in oncogene-addicted cancers, including mTOR-dependent down-regulation of MCL-1 protein levels, which we confirmed." (PMID 40316540, 2025). "Further studies are essential to fully elucidate the intricate interactions and downstream effects of these converging pathways on Mcl-1 stability, particularly in specific cancer contexts." (PMID 40841912, 2025). "Another antiapoptotic member of the BCL-2 family that has been targeted for the treatment of cancer is MCL-1." (PMID 40204952, 2025). "Activation of the PI3K/AKT pathway contributes to multidrug resistance (via ABCG2), alters the drug metabolism (via CYP3A4), and enhances cell survival (via MCL1), all of which play key roles in cancer cell resistance to chemotherapy drugs like irinotecan." (PMID 39931465, 2025). "Myeloid cell leukemia-1 (MCL-1)—an anti-apoptotic protein of the B-cell lymphoma 2 family—is commonly overexpressed in human cancers, promoting tumorigenesis and chemoresistance." (PMID 40380182, 2025). "Deeper understanding of these functions is an important future direction, especially in the light of ongoing efforts of targeting MCL1 for therapeutic intervention in cancer." (PMID 41326406, 2025). "Its action involves downregulating Mcl-1, an anti-apoptotic protein that enables the cancer cells to evade apoptosis." (PMID 39937256, 2025). "CDK9 promotes the survival of cancer cells by upregulating the expression of transient anti-apoptotic proteins, including Mcl-1." (PMID 40361480, 2025).
cancer (continued). "While MCL-1 has been reported to influence FAO in cancer cells and to localize to the IMM, its impact on cristae integrity has remained unexplored until now." (PMID 41427398, 2025). "It inhibits a myriad of signal transduction cascades (e.g. Src, EGFR, STAT-3, and Mcl-1), crucial in cancer cell proliferation and survival." (PMID 39937256, 2025). "Accumulation of lipid droplets upon MCL-1 inhibition was previously reported in cancer cells and murine liver as a marker of fatty acid β-oxidation disruption." (PMID 41427398, 2025). "Beyond direct Mcl-1 inhibition, recent findings demonstrated that marinopyrrole A has also been shown to sensitize cancer cells to tumor necrosis factor-related apoptosis-inducing ligand (TRAIL)-mediated apoptosis through a dual regulatory mechanism." (PMID 41149606, 2025). "Strikingly, we uncover potentially heretofore-undescribed methylation marks, which are sufficient to predict sensitivity to MCL1 inhibitors in pediatric cancers." (PMID 39846250, 2025). "This suggests the possibility of fluoroquinolones and Mcl-1 inhibitors synergistic mode of action, thus leading to the induction or strengthening of apoptosis in cancer cells." (PMID 40892149, 2025). "Activation of JAK-STAT signaling promotes cancer cell proliferation byregulating cyclin D1 and inhibits cell apoptosis by regulating, myeloid cell leukemia 1 (Mcl-1) and Bcl2." (PMID 40475735, 2025). "Mcl-1 is a crucial anti-apoptotic protein, frequently overexpressed in various cancers, including NSCLC, where it significantly contributes to chemoresistance." (PMID 40841912, 2025). "MCL1 is known to disrupt BAK/BAX/caspase-3,7–dependent apoptosis, and pharmacological inhibition by AZD5991/S63845 inhibits the binding of BAK and BAX to MCL1, resulting in cancer cell death." (PMID 39846250, 2025). "Cancer cells often exhibit elevated expression of Bcl-2 or Mcl-1, which stabilize the mitochondrial membrane and inhibit cytochrome C release, thereby blocking caspase-9 activation and the subsequent apoptotic cascade." (PMID 41375095, 2025). "It is well established that Bcl-XL, Bcl-2, and MCL-1 are aberrantly expressed in many cancer cell lines, enabling these cells to circumvent apoptosis." (PMID 40400713, 2025). "Cancer cells often exploit MCL-1 upregulation to evade cell death by neutralizing pro-apoptotic proteins to facilitate mitochondrial stabilization and enhance cell survival." (PMID 40380182, 2025). "These experiments suggest important clinical implications regarding the use of Mcl-1 inhibitors in cancer therapy." (PMID 40951311, 2025). "MDR1 (also known as P-glycoprotein or ABCB1) can contribute to resistance against MCL1 inhibitors by actively exporting these agents from cancer cells, reducing their intracellular levels and therapeutic efficacy." (PMID 41155156, 2025). "The Bcl-2 family contains the anti-apoptotic protein Mcl-1, which is highly expressed in numerous human cancer cell lines and up-regulated in a range of human cancer, including KC." (PMID 40834023, 2025). "Compound 2 with a α-fluorofuran moiety is a potent and selective inhibitor of the induced myeloid leukemia cell differentiation protein MCL1 and is considered a promising candidate for targeted cancer therapy." (PMID 40509193, 2025). "Recently, Mcl-1 has become a promising target in cancer therapy because Mcl-1 is considered a key factor in overcoming tumor resistance to various therapeutics." (PMID 38200153, 2024). "Bcl-2 antiapoptotic molecules (bcl-2, bcl-xL, and mcl-1) are frequently upregulated in acquired chemo-resistant cancer cells, which block drug-induced apoptosis." (PMID 38673964, 2024). "In a different study, in TNBC models including MDA-MB-231 cells, MYC and MCL1 were found to cooperatively promote paclitaxel-resistant cancer stem cells by increasing OXPHOS, reactive oxygen species (ROS) production, and HIF-1α expression." (PMID 38579004, 2024).
cancer (continued). "MCL1 is also intricately involved in regulating autophagy and ferroptosis, two additional cell death pathways with emerging attention in cancer biology." (PMID 38485916, 2024). "Mcl-1, an antiapoptotic protein, is often overexpressed in tumor cells, which hinders the success of cancer therapy." (PMID 39048945, 2024). "BCL-2 family proteins that inhibit cell death include MCL-1, BCL-xL and BCL-2, and their expression has been implicated in poor cancer patient outcome and resistance to treatment." (PMID 39497108, 2024). "For example, CDK9 is critical for the continuous expression of genes producing short-lived mRNAs or proteins, such as MYC and MCL-1 that promote cancer cell survival." (PMID 38326887, 2024). "Investigating the roles of Mcl-1 in mitochondria is a potential strategy for cancer therapy development." (PMID 39272918, 2024). "This growing attention to MCL1 as a chemotherapeutic target to treat different cancers initiated our interest in the role of this oncogene in PEL." (PMID 39386614, 2024). "The study highlights the binding dynamics and affinity of peptides to Mcl-1, especially in the context of developing novel therapeutic strategies for cancer treatment." (PMID 38928234, 2024). "STAT3 inactivation triggered by sorafenib has been shown to elicit different types of cancer cell death including apoptosis and autophagy, possible via myeloid cell leukemia-1 (MCL1) downregulation." (PMID 38485916, 2024). "Nuclear factor erythroid 2-related factor 2 (Nrf2) not only plays a definitive role in the regulation of oxidative stress but also contributes to chemoresistance, which Mcl-1 also promotes in multiple types of cancer." (PMID 39272918, 2024). "Acute oral toxicity was determined, and a molecular docking study was performed using target proteins associated with cancer, including, HMG-CoA, Bcl-2, Mcl-1, and VEGFR-2." (PMID 39769118, 2024). "This study confirmed that MCL-1 expression in normal mammary gland tissue was significantly lower, and malignant tumor tissue exhibited higher MCL-1 expression than benign tumor tissue." (PMID 39012900, 2024). "The MCL1 gene is frequently amplified in cancer and codes for the antiapoptotic protein myeloid cell leukemia 1 (MCL1), which confers resistance to the current standard of care." (PMID 39179926, 2024). "Immunohistochemistry revealed that 53% of benign tumors and 75% of malignant tumors exhibited high MCL-1 expression, whereas only 8% of normal mammary glands exhibited high MCL-1 expression." (PMID 39012900, 2024). "Although venetoclax is a selective small-molecule Bcl-2 inhibitor, it is ineffective against cancer cells with high Mcl-1 levels, including MM." (PMID 39411073, 2024). "Overcoming these challenges is essential for translating the preclinical success of MCL1 inhibitors into effective clinical cancer therapies." (PMID 39802137, 2024). "Since cancer resistance to the BCL2 inhibitor venetoclax is based on the upregulation of alternative anti-apoptotic factors such as MCL1, the suppression of both BCL2 and MCL1 by 3a appears especially promising." (PMID 39062194, 2024). "Of note, across various cancers, MYC amplification is often associated with upregulation of BCL-XL and MCL-1, rescuing cells from MYC-induced apoptosis." (PMID 38942989, 2024). "Developing specific MCL‐1 inhibitors and dual inhibitors that target multiple antiapoptotic proteins simultaneously can further overcome resistance by preventing cancer cells from compensating through alternative pathways." (PMID 39239068, 2024). "Understanding the structural basis of the interactions between these Bim-based peptides and Mcl-1 provides valuable insights for the development of novel therapeutic strategies for targeting the Bcl-2 family of proteins in cancer treatment." (PMID 38928234, 2024). "As the malignancy of the mammary gland tissues increased from normal to malignant tumors, the intensity of MCL-1 expression increased." (PMID 39012900, 2024).
cancer (continued). "We identified cardiac glycosides (CGs) as post-transcriptional MCL1 inhibitors, as MCL1 was downregulated before caspase cleavage in multiple cancer cell types." (PMID 37904054, 2024). "Myeloid cell leukemia-1 (MCL-1), which usually refers to the long isoform (MCL-1L) is frequently overexpressed in various types of cancer." (PMID 39695189, 2024). "The pro-survival protein myeloid cell leukaemia-1 (Mcl-1), a member of the Bcl-2 family, is among the most frequently upregulated genes in cancer." (PMID 38928234, 2024). "Raf1, B-Raf, EGFR, SOS1, Bad, Myc, Jun, and Mcl1 were mapped to pathways related to apoptosis or cancers." (PMID 38643189, 2024). "The development of the Mcl-1 inhibitor S63845 has enabled the selective inhibition of Mcl-1 in cancer cells, and S63845 has shown high efficacy in a panel of hematological cancer cell lines." (PMID 38542429, 2024). "Localized within mitochondria, and playing a pivotal role in regulating mitochondrial apoptotic pathways, Mcl-1 is becoming an attractive target for cancer treatment." (PMID 39372954, 2024). "We also investigated the dependency profile of BCL2 family proteins (BCL2, BCL2L10, BCL2A1, BCL2L1, and MCL1) in GBM within Cancer Cell Line Encyclopedia, and found that GBM cells show the greatest dependency on Bcl-xL (BCL2L1) for survival." (PMID 38383492, 2024). "Overall, the more studies are warranted to fully understand the potential and limitations of Mcl-1 inhibitors in cancer therapy." (PMID 39372954, 2024). "It targets cancer-causing genes such as BCL2, MCL1, and CDK6, and its reduction leads to increased cell growth and resistance to cell death." (PMID 39061157, 2024). "For example, navitoclax targets only some anti-apoptotic members of the Bcl-2 protein family but not the anti-apoptotic protein Mcl-1, which leads to overexpression of the anti-apoptotic protein Mcl-1 and rapid development of drug resistance in cancer cells." (PMID 38421832, 2024). "Mcl-1 gene, a homologous of the BCL-2 gene, encodes the full-length MCL-1 protein and is one of the most amplified genes in malignant tumors 38-40." (PMID 38706892, 2024). "Mcl-1 (myeloid cell leukemia 1), a member of the Bcl-2 family, is upregulated in various types of cancer." (PMID 38928234, 2024). "Myeloid cell leukemia-1 (MCL-1), an anti-apoptotic BCL-1 protein, has been verified to be among the most highly upregulated pathologic proteins in human cancers linked to tumor relapse, poor prognosis and therapeutic resistance." (PMID 38706892, 2024). "The relationship between MCL1 and cancer is well described in the literature, studies have shown that its overexpression contributes to cell survival and resistance to various chemotherapeutic agents." (PMID 38972247, 2024). "MCL1 is an anti-apoptotic member of the BCL2 protein family, and its overexpression is associated with poor prognosis across various cancers." (PMID 39802137, 2024). "In cancers where MCL1 is overexpressed, the excess levels of MCL1 protein can overwhelm the BH3-only proteins while still maintaining inhibition of BAX and BAK and, in this way, promote survival." (PMID 39802137, 2024). "Like other antiapoptotic Bcl-2 family members, MCL1 prevents cancer cell death by tightly binding to proapoptotic effector proteins including BAK, BAX or BOK, as well as BH3-only activator proteins such as BIM, PUMA or NOXA3–7." (PMID 39179926, 2024). "To identify putative genomic biomarkers of MCL1 sensitivity, we interrogated MCL1 gene dependency data from genome wide CRISPR/Cas9 cell viability screens using the Broad Institute’s Cancer Dependency Map (DepMap)." (PMID 38371625, 2024). "IMQ-induced expression of p-DRP1(Ser616), a mitochondrial fission marker, in BCC and AGS control cells was greater than that in Mcl-1-overexpressing cancer cells." (PMID 39272918, 2024). "Studies underscore the high dependence of AML blast cells and cancer stem cells on MCL-1 for survival and resistance." (PMID 38399263, 2024).
cancer (continued). "Certain cancer cells are proposed to have high levels of activated BAK sequestered by MCL1 or BCLXL, thus priming these cells to undergo apoptosis in response to BH3 mimetic compounds that target MCL1 or BCLXL." (PMID 38582955, 2024). "Using gene editing or BH3 mimetics to inhibit anti-apoptotic BCL-2 family proteins in TNBC line MDA-MB-231, we show that BCL-xL and MCL-1 promote cancer cell survival through compensatory mechanisms." (PMID 38898061, 2024). "In this study, we provide evidence that Mcl-1 not only protects IMQ-treated cancer cells from apoptosis but also maintains mitochondrial function and integrity to prevent IMQ-induced mitochondrial damage, ROS overproduction, and mitophagy." (PMID 39272918, 2024). "Differential regulation of MCL-1 in human primary and drug-resistant cancer cells including CLL has been reported to play a critical role in the regulation of apoptosis." (PMID 39061962, 2024). "MDM2 promoted resistance to Osimertinib through a PI3K/Akt and MAPK/Erk-independent machinery, in contrast, MDM2 selectively stabilized MCL-1 protein to arrest Osimertinib-induced cancer cell apoptosis." (PMID 39543744, 2024). "Overexpression of Mcl-1 is correlated with hightumor grade, poor survival, and both intrinsic and acquired resistanceto cancer therapies." (PMID 39102508, 2024). "This study highlights the binding dynamics and affinity of peptides to Mcl-1, especially in the context of developing novel therapeutic strategies for cancer treatment." (PMID 38928234, 2024). "The discussed results indicate targeted interventions addressing anti-apoptotic MCL1 as a new therapeutic strategy for cancers as well as other diseases." (PMID 38256213, 2024). "Given the importance of MCL-1 proteolysis for apoptosis priming, prompt destruction of MCL-1 as an immediate response to anti-cancer treatment therefore underlies sensitivity to Osimertinib in EGFR mutant NSCLC." (PMID 39543744, 2024). "The anti-cancer agent MP-A08, as a free compound, has shown promise by significantly inhibiting MCL-1 expression in AML." (PMID 38399263, 2024). "The concomitant inhibition of BCL-xL and MCL-1 clearly increases cancer cells apoptosis, highlighting the presence of compensatory mechanisms between these two proteins." (PMID 38898061, 2024). "Many studies have indicated that the expression of Mcl-1 is important for cancer cell survival during chemotherapy." (PMID 39272918, 2024). "Because Noxa binds to Mcl-1 to facilitate the release of BAK from Mcl-1, high Noxa levels sensitize cancer cells to the cytotoxic effects of ABT263 and other BH3 mimetics." (PMID 38483541, 2024). "The important role of MCL-1 in facilitating tumor progression makes it an attractive biomarker for cancer treatment." (PMID 38706892, 2024). "In order to explore the potential molecular mechanisms of the anti-tumor effect of butein, we initially examined the expression levels of the critical cancer-related protein MCL-1." (PMID 38706892, 2024). "Combined targeting EGFR and MDM2 stabilize FBW7, as a result, accelerates prompt MCL-1 protein turnover and augments cancer cell apoptosis." (PMID 39543744, 2024). "Taken together, these results indicate that Mcl-1 overexpression not only further optimized mitochondrial function but also stabilized the mitochondrial respiratory chain in IMQ-treated cancer cells." (PMID 39272918, 2024). "Anti-apoptotic Bcl-2 familymember Mcl-1 has emerged as a targetof significant interest for the treatment of cancer." (PMID 39102508, 2024). "MCL1 is often overexpressed in cancers such as leukemia, lymphoma, and solid tumors, allowing cancer cells to evade apoptosis and resist conventional treatments." (PMID 39802137, 2024).